COL6A2 (collagen type VI alpha 2 chain)
Diseases named in the same sentence as COL6A2 in open-access papers (continued):
Sharing a sentence is not in itself a finding about the gene and the disease.
amyloid (1 paper, 2018). "In addition, we identified norrin (NDP) and collagen alpha-2(VI) (COL6A2) as highly selective markers that are clearly present in CAA yet virtually absent in relation to parenchymal amyloid plaque pathology." (PMID 29860944, 2018).
Azoospermia (1 paper, 2021). Absence of any measurable level of sperm,whereby spermatozoa cannot be observed even after centrifugation of the semen pellet. "COL6A2 is associated with infertility in human Azoospermia and involved in male reproductive disorders." (PMID 34072909, 2021).
central obesity (1 paper, 2022). "Eleven types of variants in 4 genes (COL6A2, FTO, SPARC, and MTHFR) were found to be related to central obesity, and 8 of 48 subjects with MetS (16.7%) showed putative non-synonymous variants in these genes." (PMID 35999587, 2022).
colon adenocarcinoma (1 paper, 2021). "A cluster of 13 CpG loci (11 genes) were identified that displayed differential methylation in colon adenocarcinoma (COAD) (N = 289) compared to normal colon tissues (N = 38): ZNF671, TWIST1 (two CpG loci), TMEFF2, TM6SF1, GAS7, MAL, HIN1 (two CpG loci; SCGB3A1), COL6A2, AKR1B1, GPX7, ARHGEF7)." (PMID 34903270, 2021).
congenital atrial septal defect (1 paper, 2022). "Many studies have shown that the expression of COL6A2 is related to congenital atrial septal defect (ASD)." (PMID 36505882, 2022). "that COL6A2 expression is increased in congenital atrial septal defect." (PMID 36505882, 2022).
diabetes (1 paper, 2025). "These pathways are well known to participate in ECM metabolism, angiogenesis, and inflammatory regulation, indicating that COL6A2 may contribute to structural remodeling and functional impairment of the diabetic retina by modulating the ECM-integrin axis and downstream AKT activation." (PMID 41583295, 2025).
diabetic cardiomyopathy (1 paper, 2025). Diabetic cardiomyopathy is a disorder of the heart muscle in people with diabetes. "Previous research has demonstrated that the miR-29 family is downregulated in diabetic nephropathy and diabetic cardiomyopathy, where it suppresses collagen gene expression (including COL1A1, COL4A1, and COL6A2) and is closely linked to TGF-β signaling." (PMID 41583295, 2025).
disc degeneration (1 paper, 2021). "Among which, KRT19 and COL6A2 were considered as important degeneration markers in the previous studies, while the SNPs and mutations of COL11A2 are also linked to disc degeneration." (PMID 33536009, 2021).
distal myopathy (1 paper, 2024). Distal myopathy refers to a group of muscle diseases which share the clinical pattern of predominant weakness and atrophy beginning in the feet and/or hands. "Notably, in individual ITA04, two LP variants (ATP7B: c.1993A>G and COL6A2: c.1572+1G>A) were reported; we observed that these variants co-segregated in their relatives diagnosed with SFN and distal myopathy." (PMID 39000354, 2024).
Ewing sarcoma (1 paper, 2022). A small round cell tumor that lacks morphologic, immunohistochemical, and electron microscopic evidence of neuroectodermal differentiation. "Through our investigation, we confirmed that MGST1 and the new marker COL6A2 are both produced by doxorubicin-resistant cells and demonstrated clinical significance for the survival of patients with Ewing sarcoma." (PMID 36428591, 2022).
Fabry disease (1 paper, 2025). Fabry disease (FD) is a progressive, inherited, multisystemic lysosomal storage disease characterized by specific neurological, cutaneous, renal, cardiovascular, cochleo-vestibular and cerebrovascular manifestations. "Conversely, genes crucial for ECM integrity and maintenance, including ADAMTS5, LOXL1, COL1A1, and COL6A2, were all down-regulated in the patient hURECs, indicating dysregulated ECM dynamics, as previously observed in Fabry disease." (PMID 40673439, 2025).
gliosarcoma (1 paper, 2019). A rare histological variant of glioblastoma (WHO grade IV) characterized by a biphasic tissue pattern with alternating areas displaying glial and mesenchymal differentiation (WHO). "When compared to GBMs, gliosarcomas show up-regulation of some genes, ranging up to a 6-fold difference on a log2-scale and most top differentiating genes encode collagens (COL1A1, COL6A1, COL6A2, COL6A3, COL1A2, COL3A1)." (PMID 30818875, 2019).
glomerulosclerosis (1 paper, 2021). A hardening of the kidney glomerulus caused by scarring of the blood vessels. "Consistent with marked glomerulosclerosis in UNx-Renin mice, ECM-associated gene expression changes were more pronounced in UNx-Renin mice, in which additional markers of fibrogenesis were significantly upregulated, including Col1a1, Col3a1, Col6a1, Col6a2 and Mmp7." (PMID 34494644, 2021).
hereditary cardiomyopathy (1 paper, 2021). "These genes include VCP, COL6A2, SYNE2, PYGM gene, and TPM2, and they warrant investigation of the more complex interacting mechanism underlying the hereditary cardiomyopathy phenotypic features." (PMID 33567613, 2021).
intervertebral disc degeneration (1 paper, 2025). "Next, an investigation was conducted to determine if ZEB2 acts as a potential key transcription factor in regulating TNFAIP6 and COL6A2 in intervertebral disc degeneration." (PMID 39704340, 2025). "In order to validate the potential transcription factor regulatory network, we conducted an analysis of the expression levels of IL-1β, ZEB2, TNFAIP6, and COL6A2 in intervertebral disc degeneration (IVDD) patients." (PMID 39704340, 2025).
laryngeal carcinoma (1 paper, 2020). Carcinoma that arises from the laryngeal epithelium. "In our RNA-seq results, COL6A1, COL6A2, and COL6A3 were downregulated at mRNA levels in MYCT1 overexpressing laryngeal cancer cells (GSE123275)." (PMID 33680912, 2020). "COL6A2 and COL6A3 knockdown significantly recued the effects of MYCT1 silence on the adhesion, migration and wound healing abilities of the laryngeal cancer cells (P < 0.01), respectively." (PMID 33680912, 2020). "At the mRNA level, Knockdown of MYCT1 significantly increased the COL6A1, COL6A2, and COL6A3 expression but MYCT1 decreased the COL6A2, and COL6A3 expression in laryngeal cancer cells (P < 0.01), respectively." (PMID 33680912, 2020). "We also found that both COL6A2 and COL6A3 knockdown significantly recued the effects of MYCT1 silence on their expressions in laryngeal cancer cells (P < 0.01), respectively." (PMID 33680912, 2020). "In MYCT1-overexpressing laryngeal cancer cells, another 13 DEGs (GSE123275) were overlapped in the GSE6631 and TCGA datasets, where COL6A1, COL6A2, and COL6A3 were also present." (PMID 33680912, 2020). "This implies that COL6A1, COL6A2, and COL6A3 are crucial in laryngeal cancer." (PMID 33680912, 2020).
lung fibrosis (1 paper, 2020). "In keeping with this, colonic macrophages from ILC-depleted mice showed an increase in Col6a1, Col6a2, and Col6a3 transcripts that together form trimers that make up collagen type VI, previously shown to promote myofibroblast activation in the context of lung fibrosis." (PMID 32640223, 2020).
lymph node metastasis (1 paper, 2025). "Moreover, increased COL6A2 expression was positively associated with aggressive clinicopathological features of ccRCC, such as advanced T stage, lymph node metastasis, higher histological grade, and later pathological stage." (PMID 41323784, 2025). "These analyses revealed that higher COL6A2 expression was significantly associated with an increased likelihood of higher T stage (OR = 2.901), lymph node metastasis (OR = 1.574), distant metastasis (OR = 1.257), later pathological stage (OR = 1.294), and advanced histological grade (OR = 1.838)." (PMID 41323784, 2025).
metastatic tumor (1 paper, 2025). "Expression of COL2A1, COL11A1, COL6A1, COL6A2 and LUM tended to be higher in primary/metastatic tumor than in normal tissue." (PMID 40927672, 2025).
osteoporosis (1 paper, 2025). A condition of reduced bone mass, with decreased cortical thickness and a decrease in the number and size of the trabeculae of cancellous bone (but normal chemical composition), resulting in increased fracture incidence. "By integrating cis-eQTL, pQTL, and RNA-seq data, four candidate genes were identified with significant causal effects on osteoporosis risk, including COL6A2, CPXM1, MGP, and SPARC." (PMID 41029778, 2025). "COL6A2 and CPXM1, both associated with extracellular matrix composition and remodeling, were found to increase susceptibility to osteoporosis, whereas SPARC exhibited a protective effect, consistent with its known roles in bone matrix mineralization and osteoblast function." (PMID 41029778, 2025).
pancreatic ductal adenocarcinoma (1 paper, 2024). An infiltrating adenocarcinoma that arises from the epithelial cells of the pancreas. "Analysis of TCGA PanCancer RNA sequencing data revealed that, like in sarcomas, COL6A1, COL6A2, and COL6A3 are highly expressed in pancreatic ductal adenocarcinoma (PDAC)." (PMID 38652549, 2024).
Prader-Willi syndrome (1 paper, 2022). "A positive CMA confirmed Prader-Willi syndrome (paternal deletion) and pursuing testing for the familial history by ES identified a pathogenic variant in COL6A2 in mother and son confirming a diagnosis of Ulrich congenital muscular dystrophy." (PMID 36360262, 2022).
progressive myoclonus epilepsy (1 paper, 2020). A rare group of disorders characterized by the development of myoclonic and tonic-clonic epileptic seizures associated with progressive degeneration of the nervous system. "Mutations in COL6A2 were linked to progressive myoclonus epilepsy 73, and COL6A1 was reported within a set of genes that are upregulated in the human cerebral cortex with respect to non‐human primates, indicating a human‐specific role of this gene in brain development and evolution." (PMID 32207244, 2020).
ptosis (1 paper, 2022). The drooping of the upper eyelid. "In this patient, the expression of collagen VI on skin and muscle biopsy has not been evaluated and muscle MRI was not performed, limiting the significance of this variant in COL6A2 and its association with ptosis and COL6-RM." (PMID 36498898, 2022).
renal fibrosis (1 paper, 2020). A final common manifestation of a wide variety of chronic kidney diseases characterized by glomerulosclerosis and tubulointerstitial fibrosis. "Further, rats that were fed the HP-HCa2+ diet expressed lower levels of four key markers of renal damage and fibrosis (NGAL, COL1A1, COL6A2, and MPG) and exhibited decreased renal fibrosis revealed by Masson’s trichrome staining to detect collagen." (PMID 32271147, 2020).
virus infection (1 paper, 2023). "The top 4 were “Cell matrix adhesion and organization” (COL6A1, COL6A2, COL18A1, JAM2, ADAMTS5 and POFUT2), “Immune/virus infection response” (MX1 and MX2), “Histone modification and chromatin remodeling” (NRIP1) and “Glycerolipid and lipid metabolism” (AGPAT3)." (PMID 38095646, 2023).
tumor (36 papers, 2012 to 2025). "A PPI network was constructed using STRING, and the associations of COL6A2 with tumor-infiltrating immune cells and immune genes were analyzed in the CIBERSORT and TISIDB databases." (PMID 36505882, 2022). "The result was independently validated in two GEO datasets—GSE167093 (254 paired samples) and GSE40435 (101 paired samples)—where tumour tissues likewise displayed significant COL6A2 up-regulation." (PMID 41323784, 2025). "Three type VI COLs (encoded by COL6A1, COL6A2, and COL6A3) and two type I COLs (encoded by COL1A1 and COL1A2) constituted a significant proportion of the human colon ECM in NAT (55.6%) and tumor (31.8%) tissues." (PMID 40032993, 2025). "The present study, which focused on elucidating the role of COL6A2 in ccRCC, provides compelling evidence of its marked upregulation across both clinical tumor specimens and in vitro cell line models." (PMID 41323784, 2025). "Analysis of the TCGA-KIRC cohort revealed differential COL6A2 transcript expression both in an unpaired comparison of 539 ccRCC tumors against 72 normal tissues and in a paired analysis of 72 matched tumor and adjacent normal specimens." (PMID 41323784, 2025). "For example, collagens, such as COL1A1, COL1A2, COL3A1, COL5A2, COL6A1, COL6A2, and COL6A3 are thought to mediate tumor progression and are associated with a poor prognosis in BCa." (PMID 37277784, 2023). "Detection of COL6A2 co-expression with immune genes using immunohistochemical methods, and tumor modeling using nude mice for prevention and treatment studies." (PMID 36505882, 2022). "A heatmap profiles showed that CTSK, MMP9, CKB, CCL18 and COL6A2 were upregulated in macrophages in tumor tissues." (PMID 36466840, 2022). "Therefore, elevated COL6A2 expression in ccRCC likely facilitates tumor progression by enhancing cellular proliferation and promoting EMT-mediated invasiveness." (PMID 41323784, 2025). "COL6A2 demonstrated significant upregulation across the different categories of fibrotic patients in the mesenteric metastases compared to both the primary tumour and normal SI." (PMID 40998421, 2025). "One approach is the direct inhibition of the interaction, either at the receptor level using agents targeting β1 integrins or, more specifically, by disrupting the COL6A2-integrin interface with monoclonal antibodies or decoy peptides once tumor-selective epitopes are defined 46-49." (PMID 41323784, 2025). "Immunohistochemistry can well demonstrate the co-expression of COL6A2 with immune genes in a tumor model established in nude mice, showing that interference with COL6A2 expression may have an inhibitory effect on tumors." (PMID 36505882, 2022). "We found COL6A2 was positively correlated with most immune cells in a tumor-immune microenvironment, which could support the highly immunogenic nature of COL6A2 in BCa." (PMID 35127724, 2021). "Down-regulation of COL6A2 induced by decreased IDO1 could suppress host anti-tumor immune response through inhibiting immune-related pathways." (PMID 35127724, 2021). "In addition, proteins observed to be absent in tumor scaffolds in the LKB1 overexpressing cell line included those associated with the adipose matrix (COL6A2) and regulators of adipogenesis (IL17RB and IGFBP4), suggesting a role for LKB1 in tumor-mediated adipogenesis." (PMID 35755802, 2022). "Through regulating pathways such as EGFR, MAPK/ERK, and PI3K/AKT, COL6A2 contributes to epithelial-mesenchymal transition (EMT), drug resistance, and immune evasion, thereby promoting tumor invasiveness and correlating with poor prognosis." (PMID 41323784, 2025). "The EZH2/PRC2|miR-3189|COL6A2 axis drives EMT and tumor progression, highlighting its potential as a therapeutic target in GBM." (PMID 40565099, 2025). "We found that the EDEM3 expression in epithelial cells (marked by KRT18, EPCAM, KRT8) was significantly higher in tumour tissues with a large proportion of CAFs (marked by COL1A1, COL1A2, COL6A1, COL6A2) in the GSE188711 CRC dataset." (PMID 39754316, 2025).
tumor (continued). "In order to understand, both FAP polyps and tumor samples were stained with VCAN (inflammatory marker), PDPN (CAF marker) and COL6A2 (normal fibroblast/basal lamina marker) and imaged." (PMID 39605357, 2024). "Not only were many collagen genes overexpressed in tumor progression between T1 and T2 stages, but also the mRNA expression of these collagen genes, such as COL1A1, COL1A2, COL3A1, COL5A1, COL5A2, COL6A2, and COL6A3, was highly positively correlated." (PMID 36596829, 2023). "We then analyzed the expression profiles of COL1A1, COL4A1, and COL6A2 in TAF and ITGA2, ITGAV, and ITGA1 in tumor cells." (PMID 35322024, 2022). "Our results showed that the methylation levels of COL6A1/2/3 in tumor tissues were significantly lower than in normal tissues, as follows: COL6A1 in ESCA, BRCA, UCEC, and PRAD; COL6A2 in LIHC, HNSC, KIRP, and BLCA; COL6A3 in HNSC, BRCA, UCEC, COAD, and PRAD." (PMID 36167487, 2022). "Col1a1, Col1a2, Col2a1, Col3a1, and Col5a2, which were commonly found in normal ECM of mouse, pig, and human breast tissues, were also identified in tumor ECM in addition to Col4a2, Col5a1, Col6a1, Col6a2, Col6a3, and Col7a1." (PMID 36547361, 2022). "We found ACAP1, IFIT3 and TAP1 were upregulated in tumor samples, while ADAMTS9, COL6A2, FBN1 and FSTL1 were downregulated in tumor specimens." (PMID 34112144, 2021). "In 10 clinical ccRCC samples from our institution, COL6A2 protein level was consistently higher in tumor tissues compared to the corresponding adjacent non-neoplastic tissue." (PMID 41323784, 2025). "In The Cancer Genome Atlas (TCGA) pancancer database, LUAD is one of multiple tumor types in which Col6a3 mRNA levels are higher in malignant than normal tissues, whereas Col6a1 and Col6a2 are not differentially expressed." (PMID 40166934, 2025). "Crosstalk between various cellular functions mediated by COL6A2 and MGST1 coordinates tumor cell vulnerability and might define the severity of the ES cells’ damage." (PMID 36428591, 2022). "However, these genes had higher methylation levels in tumor tissues, including COL6A1 in KIRC, HNSC, THCA, KIRP, and COAD; COL6A2 in KIRC, LUSC, and BRCA; COL6A3 in LIHC and KIRC." (PMID 36167487, 2022). "Substantial differences between tumor and neighboring healthy cortex were found in both interstitial matrix proteins, such as collagen 6 (COL6A1, COL6A2, COL6A3), and basement membrane components such as collagen 4 (COL4A1, COL4A2) and laminins (LAMA5, LAMA4, LAMB1, LAMB2, LAMC1)." (PMID 34884982, 2021). "Hence, based on the overlapped upstream miRNAs and correlation analysis, we confirmed that the three key miRNAs (hsa-miR-124-3p, hsa-miR-26b-5p, and hsa-miR-192-5p) could regulate the four hub genes (CAV1, COL6A2, CSPG4, and PCOLCE) in GEM-resistance and tumor immune microenvironment." (PMID 35127724, 2021). "Consistently, single-cell RNA-seq analysis of nonmalignant tumor tissues and HGOSC tissues was utilized to investigate the distribution of SFRP2 in TME and a novel subset with the highest enrichment of SFRP2 and CAF markers (COL6A1, COL6A2, FAP) was identified." (PMID 38069266, 2023).